TNF (tumor necrosis factor)
Diseases named in the same sentence as TNF in open-access papers (continued):
Sharing a sentence is not in itself a finding about the gene and the disease.
type 2 diabetes (926 papers, 2004 to 2026). "These mediators, which include C-reactive protein, interleukin-6 (IL-6), and TNF-α, raise the risk of developing chronic diseases like type 2 diabetes and cardiovascular disease." (PMID 40509530, 2025). "The ability of BRI to predict type 2 diabetes and cardiovascular risk stems from its accuracy in estimating visceral adiposity, which produces adipokines and inflammatory cytokines such as TNF-α, IL-6, and resistin, which impair insulin signaling pathways." (PMID 40727914, 2025). "Vitamin D and calcium supplementation through a drinkable yogurt has been associated with a decrease in serum levels of IL-1β and TNF-α in patients with type II diabetes mellitus." (PMID 41141350, 2025). "For instance, clinical trials have demonstrated that a BW-based diet can prevent the increase in interleukin (IL)-6 levels caused by type 2 diabetes and the tumor necrosis factor (TNF)-α, which are key inflammation markers." (PMID 39861525, 2025). "A similar study showed that chronic exposure to BaP can increase the risk of type 2 diabetes by inducing pro-inflammatory cytokines such as IL-1beta and TNF-alpha." (PMID 39108652, 2024). "A significant association between TNF and eGFR was observed in individuals with type 2 diabetes, potentially serving as indicators of disease progression." (PMID 38791060, 2024). "In one study, 500 mg of quercetin supplementation in women with type 2 diabetes led to a reduction in inflammatory markers TNF-α and IL-6, both of which are strongly associated with cardiovascular disease, indicating its potential benefits." (PMID 39539361, 2024). "In vitro, TNF-α has been shown to increase the transcriptional activity of TCF7L2 (a gene that has consistently been associated with type 2 diabetes) leading to reduced adipogenesis." (PMID 37215099, 2023). "A more recent meta-analysis however, found the TNF-α −308G/A variant to be associated with susceptibility to type 2 diabetes." (PMID 37215099, 2023). "Recently, TNF-α signaling pathway in cardiomyocytes were associated with Ca2+ signaling in Type II diabetes obese (db/db) mice." (PMID 36804872, 2023). "Metformin administration ameliorates the inflammatory response associated with diabetic nephropathy in type 2 diabetic mice by reducing the increases in NF-κB and serum levels of proinflammatory cytokines (IL-1β and TNF-α)." (PMID 35855344, 2022). "Testosterone replacement therapy to testosterone-deficient men undergoing type 2 diabetes decreases the synthesis of the proinflammatory cytokines IL-1β, IL-6 and TNF-α in antigen-presenting cells." (PMID 36551196, 2022). "Further, TNF-α has been associated with diseases (e.g., artherosclerosis, type 2 diabetes, sarcopenia) often related to pathological aging, as well as dementia and all-cause mortality." (PMID 34489672, 2021). "von Scholten and colleagues found that tumor necrosis factor-α is a powerful determinant of cardiovascular disease in patients with type 2 diabetes and is independently associated with vascular calcification mortality." (PMID 34631895, 2021). "A recent study showed that elevated salivary levels of C-reactive protein and TNF-α have been significantly associated with type 2 diabetes." (PMID 34829612, 2021). "We previously demonstrated that serum uric acid is negatively associated with eGFR and positively associated with TNF-related markers such as TNFα and TNFRs in patients with IgA nephropathy and type 2 diabetes." (PMID 34322499, 2021). "Biomarkers of pro-inflammatory cytokines, including TNF-α and IL-6, are elevated in type-2 diabetes associated with the acceleration of atherosclerosis progression." (PMID 32957558, 2020). "The study results suggest that circulating serine protease activity is significantly elevated and associated with HBA1c, HOMA-IR, TNF-α, and adiponectin levels in patients with type 2 diabetes." (PMID 32015418, 2020).
type 2 diabetes (continued). "Using the ROC analysis, four biomarkers (urinary Tf, IgG, NGAL, and TNF-α) showed diagnostic value in terms of high AUC, in type 2 diabetic patients with DN." (PMID 31218128, 2019). "Type 2 diabetes is associated with subclinical inflammation as indicated by the increase of circulating proinflammatory cytokines as such as TNF-α, IL-6, IL-1ß or IL-18." (PMID 29121068, 2017). "ELISA showed that, compared with the control group, patients with type 2 diabetes had a remarkably higher level of TNF-α (P < 0.05), and such increase was associated with levels of LncRNA NONRATT021972 (P < 0.05)." (PMID 28928602, 2017). "Risk factors for type 2 diabetes (e.g., glucolipotoxicity, TNF-α and LPS) activate Src in pancreatic β cells." (PMID 27349479, 2016). "Previous studies conducted to assess variations in inflammatory markers associated with type 2 diabetes in urban populations have indicated a significant difference in the levels of interleukin 6 (IL-6) and tumour necrosis factor α (TNF-α)." (PMID 26391589, 2015). "Accumulated adipose tissue-induced dysregulated production of adipocytokines occurring in visceral obesity associated with type 2 diabetes has been reported to induce the production of proinflammatory cytokines, including TNF-α, and augment oxidative stress." (PMID 25945116, 2015). "It is well know that COPD patients have a higher risk of developing type II diabetes compared to normal subjects, due to the increase in circulating cytokines, in particular TNF-α, that interferes with glucose metabolism and insulin sensitivity." (PMID 25973198, 2015). "Type 2 diabetes is also associated with low-grade inflammation and increased levels of proinflammatory cytokines such as TNF-α." (PMID 24692847, 2014). "PEDF is positively associated with tumor necrosis factor-α (TNF-α) in serum of type 2 diabetic patients in Japanese." (PMID 24367624, 2013). "Our group also showed association of TNF-LTA locus variants with type 2 diabetes in this population." (PMID 21849023, 2011). "In rats with type 2 diabetes, fgl2 was found to be highly expressed in renal capillaries, which led to renal microthrombosis and the expression was associated with TNF-α." (PMID 23554679, 2011). "High serum TNF-alpha level in Type 2 diabetic patients with microangiopathy is associated with eNOS down-regulation and apoptosis in endothelial cells." (PMID 20209122, 2010). "Elevated TNF-α indicates the activated innate immune system followed by chronic systemic inflammation associated with type 2 diabetes." (PMID 21189913, 2010). "Elevated TNF-α inhibits the uptake of free fatty acids from circulation and accelerates the lipolysis in adipose tissue, leading to weight loss in type 2 diabetes." (PMID 21189913, 2010). "In patients with type 2 diabetes and a high cardiovascular risk, 30 days of therapy with empagliflozin reduced IL-1β and TNF-α production by human macrophages generated from PBMC ex vivo in presence of M-CSF; serum levels of IL-18 and IL-1β were decreased as well." (PMID 40004134, 2025). "Parameters indicative of chronic inflammation, such as high-sensitivity C-reactive protein, interleukin-6, and TNF-α, are significantly and independently associated with increased serum prolactin concentrations in type 2 diabetes, chronic kidney disease, and chronic heart failure." (PMID 40650124, 2025). "In addition, anthocyanins inhibit low‐grade chronic inflammation by inhibiting the inflammatory mediators TNF‐α, IL‐6, and NF‐κB signaling pathways implicated in the progression of type 2 diabetes." (PMID 40918166, 2025). "Notably, CDAI has been associated with elevated levels of tumor necrosis factor-α and interleukin-1β, and an even closer relationship with hypertension, type 2 diabetes mellitus, and cardiovascular disease has been reported." (PMID 40732969, 2025).
type 2 diabetes (continued). "Moreover, some polymorphisms of the TNF gene in humans have been associated with the development of obesity, type 2 diabetes mellitus (T2DM), and metabolic syndrome." (PMID 39125666, 2024). "These TNF-α variants have been studied in association with the outcome of type 2 diabetes." (PMID 37215099, 2023). "High concentrations of tumor necrosis factor-α (TNF-α) are associated with coma." (PMID 35959375, 2022). "For instance, patients treated with corticosteroids or TNF antagonists have increased risk of infection, and corticosteroid use increases both the risk of fracture and the risk of developing type II diabetes." (PMID 36313344, 2022). "In addition, these chronic inflammatory markers (IL-6, CRP, and TNF-alpha, among others) are associated with several different diseases, including infection, cardiovascular disease, and type 2 diabetes mellitus (T2DM)." (PMID 35053667, 2022). "Evidence has shown that TNF-α is associated with a variety of age-associated morbidities, including atherosclerosis, dementia, type 2 diabetes, and sarcopenia, as well as mortality." (PMID 34489672, 2021). "The serum levels of superoxide dismutase, an antioxidant, was significantly increased, which was associated with decreased inflammation (hsCRP, TNF-α, IL-6) following 3 g/day taurine supplementation for 8 weeks (n = 50) in type-2 diabetic patients compared to control subjects." (PMID 32957558, 2020). "For example, polymorphisms in tumor necrosis factor-alpha (TNF-α), or the anti-inflammatory adipokine, adiponectin, were more prevalent among persons of African ancestry and were linked to an increased risk for type 2 diabetes." (PMID 33023586, 2020). "Epidemiological studies have reported that levels of pro-inflammatory and inflammatory cytokines such as C-reactive protein (CRP), TNF-α, IL-1β, and IL-6 were elevated in patients with type 2 diabetes and were associated with the development of type 2 diabetes." (PMID 30857216, 2019). "TNF expression in adipose tissues increases in obese and type 2 diabetes animal specimens, and has been confirmed in human specimens closely associated with type 2 diabetes, especially in obese subjects." (PMID 31275881, 2019). "In PBMCs, the expression of genes encoding TNF-α and IL-6 was elevated in individuals with type 2 diabetes with micro- (n = 29) and macroalbuminuria (n = 31) compared with the control group (n = 22) and individuals with type 2 diabetes and normoalbuminuria (n = 18)." (PMID 29159468, 2018). "In conclusion, while the consumption of a high GI diet for 30 consecutive days caused an increase in fructosamine, NEFA and TNF-α concentrations, consuming a low GI diet caused a significant reduction of approximately 2% in body fat among overweight patients with type 2 diabetes." (PMID 27598983, 2017). "In addition to the studies on rodents, work in humans with artherosclerosis demonstrated that significantly increased serum TNFα levels in patients were associated with impaired glucose tolerance and type 2 diabetes, after correcting for other variables." (PMID 23592917, 2013). "Lack of skeletal muscle PGC-1α seems however to impair the acute TNFα response, which may reflect a phenotype more susceptible to infections as also observed in type 2 diabetes patients." (PMID 22384185, 2012). "Previous studies have implicated TNF-α plasma levels with type II diabetes." (PMID 19558671, 2009). "Novel data have now appeared showing that the concomitant presence of the promoter polymorphisms of TNF-α and IL-6, linked to high production of these cytokines increases the risk of conversion to type 2 diabetes in obese subjects with impaired glucose tolerance response." (PMID 15904534, 2005). "It was previously reported that TNF-α interferes with the insulin receptor signaling pathway and with metabolism of glucose transporters, and in consequence may be linked to the etiology of type-2 diabetes." (PMID 37514235, 2023).
type 2 diabetes (continued). "Moreover, an ephedrine-rich extract had an impressive euglycemic effect in an obese type 2 diabetes experimental model, which was linked to lower tumor necrosis factor (TNF-α) expression and higher peroxisome proliferator-activated receptor (PPAR-γ) expression." (PMID 35684137, 2022). "A clinical study in men with type 2 diabetes who developed partial testosterone deficiency showed testosterone immunosuppressive activity in reducing the synthesis of the proinflammatory cytokines IL-1β, IL-6 and TNF-α, an effect that persists after termination of testosterone treatment." (PMID 36551196, 2022). "In addition, excess TNF-α production is positively associated with type 2 diabetes." (PMID 35447934, 2022). "Furthermore, vitamin D could decrease AGEs and TNF-α serum levels in type 2 diabetic patients with vitamin D deficiency or insufficiency." (PMID 31673295, 2019). "However, only ASE associated with exercise training reduced TNF-α serum levels in type 2 diabetic rats, which may contribute to the improvement of insulin sensitivity." (PMID 29920546, 2018). "Also TNF (tumor necrosis factor) has been implicated in the development of type 2 diabetes." (PMID 27019061, 2016). "Furthermore, inflammatory cytokines such as TNF has been linked to pericyte apoptosis and inhibition of TNF reduced pericyte ghost formation with decreased acellular capillary formation caused by type 1 and type 2 diabetes." (PMID 24795699, 2014). "Twelve weeks of HIIT lower IL-6 and TNF-α in obese adolescents and type 2 diabetes patients, while enhancing IL-10 secretion to support anti-inflammatory capacity." (PMID 40777031, 2025). "Several meta-analyses reported that GLP-1RAs reduced inflammatory biomarkers, such as C-reactive protein (CRP) and TNFα, and oxidative stress biomarkers, such as malondialdehyde, in subjects with type 2 diabetes." (PMID 39861190, 2025). "For instance, probiotics and synbiotics have shown efficacy in lowering pro-inflammatory cytokines in prediabetes and type 2 diabetes, with a 2023 randomized trial demonstrating significant IL-6 and TNF-α reductions over 12 weeks." (PMID 41465826, 2025). "NF-κB drives the transcription of the inflammatory molecules TNF-α and IL-6, which facilitates the dysfunction in Type 2 Diabetes (T2D)." (PMID 40943351, 2025). "In humans, the infusion of TNF-alpha has been found to decrease muscle insulin sensitivity and glucose uptake, providing evidence of its role in the development of type 2 diabetes." (PMID 40218888, 2025). "Pomegranate juice was shown to lower circulating IL-6 and TNF-α in individuals with type 2 diabetes, while a polyphenol-rich jelly drink reduced TNF-α after eight weeks in dyslipidemic adults." (PMID 41465047, 2025). "NSPT was associated with a significant reduction in high-sensitivity C-reactive protein (hs-CRP) and proinflammatory cytokines (IL-6, TNF-α), as well as with decreased HbA1c levels, particularly in patients with type 2 diabetes." (PMID 40842443, 2025). "Increased TNF-α concentration also correlates with increased HbA1C concentration in patients with type 2 diabetes, which indicates its significant role in the development of hyperglycemia." (PMID 40904859, 2025). "In a controlled trial involving men with type 2 diabetes, weekly semaglutide administration for 6 months resulted in statistically significant decreases in circulating TNF-α and IL-6, demonstrating direct anti-inflammatory benefits." (PMID 41511355, 2025). "Another study showed that indoleacrylic acid (an indole derivative) alleviates type 2 diabetes by activating the aryl hydrocarbon receptor (AhR), which reduces IL-1β, IL-6, and TNF-α levels." (PMID 41156481, 2025). "Clinical studies using the IL-1 receptor antagonist anakinra have shown modest improvements in glycemic control and β-cell function in individuals with type 2 diabetes, demonstrating more encouraging results than TNF-α blockade." (PMID 41463063, 2025).
type 2 diabetes (continued). "Previous studies have reported that cold exposure increases systemic inflammatory cytokines such as IL-1β, IL-6, and TNF-α in patients with type 2 diabetes." (PMID 40270542, 2025). "In elderly sarcopenic patients with type 2 diabetes, Gln administration has been shown to reduce circulating TNF-α levels." (PMID 41003011, 2025). "In this regard, circulating monocytes exhibit a higher capacity to produce TNF-alpha in obesity and type 2 diabetes (T2D), both conditions characterized by elevated LPS and LBP serum levels." (PMID 41383632, 2025). "This includes sleep apnea, type 2 diabetes, coronary heart disease, respiratory system disorders, and pain syndromes, like osteoarthritis that is exacerbated nocturnally by TNFα, IL-1β, and other somnogenic immunological modulators." (PMID 40137093, 2025). "TNF-alpha and IL-1β, key pro-inflammatory cytokines, play significant roles in the dysfunction of cells within the islets of Langerhans in type 2 diabetes." (PMID 40182806, 2025). "The obese mice have hyperlipidemia, systemic inflammation as indicated by high serum TNF-α level, type 2 diabetes as indicated by hyperglycemia and hyperinsulinemia." (PMID 39310104, 2024). "In subjects with type 2 diabetes, a diet high in AGEs increased inflammatory markers, i.e., C-Reactive protein, TNF-α, VCAM-1 and oxidative stress." (PMID 39518960, 2024). "Danggui Buxue decoction (DBD) significantly reduced the levels of TNF-α, IL-1β in serum from GK rats with type 2 diabetes." (PMID 39711801, 2024). "Hesperidin also alleviated neuroinflammation through the reduction of IL1-β and TNF-α in patients with type 2 diabetes." (PMID 38794179, 2024). "The results of an investigation demonstrated astrong correlation between type 2 diabetics and TNFα, IL-6, CRP, and IL-10, receiving care at SMHS Hospital who is of Kashmiriorigin." (PMID 39132231, 2024). "Diabetes type 2 (T2D) is a chronic inflammatory disease characterized by insulin resistance, upregulated circulating TNF, interleukin, and adipokines levels." (PMID 38177104, 2024). "Curcumin decreased expression of MCP-1, IL-1β, and TNF-α leading to anti-inflammatory responses in type 2 diabetic patients." (PMID 38791060, 2024). "Elevated levels of inflammatory markers such C-reactive protein (CRP), interleukin-6 (IL-6), and tumor necrosis factor-α (TNF-α) are commonly observed in patients with type 2 diabetes." (PMID 39224122, 2024). "Hesperidin led to notable decreases in the levels of TNF-α and IL-6 in type 2 diabetes patients, while a hesperidin-derived metabolite suppressed endothelial cell inflammation." (PMID 39203784, 2024). "The goal of the research is to ascertain howTumour Necrosis Factor (TNFα), Type 2 diabetes has several etiopathogenic factors, including Interleukin-6 (IL-6), Interleukin-10(IL-10), and C - reactive protein (CRP)." (PMID 39132231, 2024). "TNF-α is of utmost importance due to its involvement in the causation of both OSCC and diabetes of type 2." (PMID 38406163, 2024). "Systolic blood pressure was also correlated with TNFα levels in both Canadian men and women with type 2 diabetes." (PMID 38256155, 2024). "Previous studies have detected higher expression of TLR4 and TNF-α in obese as compared to lean subjects with a remarkably higher expression in obese and overweight individuals with type 2 diabetes." (PMID 37964189, 2023). "Multiple taxa priorly associated with cardiovascular disease and type 2 diabetes were linked with specific cytokines (e.g., greater Enterococcus and IL-5 and TNF-a, lower Coprococcus and TNF-a), possibly indicating a shift to a more inflammatory state." (PMID 36609477, 2023). "IL-1 together with TNFα inhibits insulin synthesis, suppresses insulin-induced secretion, and induces apoptosis in pancreatic β-cells, leading to type 1 and type 2 diabetes." (PMID 36647426, 2023). "TNFα and IL1β have been independently pursued as therapeutic targets in clinical trials for type 2 diabetes and systemic insulin resistance." (PMID 37400454, 2023).